NEK7 (NIMA related kinase 7)
Description:
Protein kinase which plays an important role in mitotic cell cycle progression. Required for microtubule nucleation activity of the centrosome, robust mitotic spindle formation and cytokinesis. Phosphorylates EML4 at 'Ser-146', promoting its dissociation from microtubules during mitosis which is required for efficient chromosome congression. Phosphorylates RPS6KB1 (By similarity). Acts as an essential activator of the NLRP3 inflammasome assembly independently of its kinase activity. Acts by unlocking NLRP3 following NLRP3 tranlocation into the microtubule organizing center (MTOC), relieving NLRP3 autoinhibition and promoting formation of the NLRP3:PYCARD complex, and activation of CASP1. Serves as a cellular switch that enforces mutual exclusivity of the inflammasome response and cell division: interaction with NEK9 prevents interaction with NLRP3 and activation of the inflammasome during mitosis.
Tractability: Small molecule: a structure with a bound ligand is known; a high-quality ligand is known; it has a binding pocket of medium quality; it belongs to a druggable protein family. PROTAC: ubiquitination databases record sites on it; its protein half-life has been measured; a small molecule that binds it is known.
Target class: Other protein kinase NEK family; Kinase; Enzyme; Other protein kinase group; Protein Kinase
Gene: Protein-coding gene on chromosome 1 (198,156,883 to 198,322,451, forward strand). Ensembl gene ENSG00000151414.
Subcellular location: Nucleus; Cytoplasm; Cytoplasm, cytoskeleton, spindle pole; Cytoplasm, cytoskeleton, microtubule organizing center, centrosome
Subcellular location (Human Protein Atlas): Nucleoplasm
Pathways (Reactome):
Cell Cycle: Activation of NIMA Kinases NEK9, NEK6, NEK7; EML4 and NUDC in mitotic spindle formation; Nuclear Pore Complex (NPC) Disassembly
Gene Ontology:
Molecular function: molecular function activator activity; protein binding; protein serine kinase activity; protein serine/threonine kinase activity; ATP binding; protein kinase activity
Biological process: positive regulation of NLRP3 inflammasome complex assembly; positive regulation of telomere maintenance; protein phosphorylation; regulation of kinase activity; regulation of mitotic cell cycle; cellular response to potassium ion; spindle assembly; regulation of chromosome organization
Cellular component: cytoplasm; microtubule organizing center; nucleoplasm; nucleus; centrosome; spindle pole
Genetic constraint (gnomAD): Loss-of-function variants: 4 observed, 8.75 expected, observed/expected ratio (o/e) 0.46, 90% interval 0.22 to 1.04. That is too few expected variants to judge how well the gene tolerates losing a copy. Missense variants: 58 observed, 92.61 expected, observed/expected ratio (o/e) 0.63, 90% interval 0.51 to 0.78. Synonymous variants: 29 observed, 33.15 expected, observed/expected ratio (o/e) 0.87, 90% interval 0.65 to 1.19.
Homologues: Orthologues: chimpanzee NEK7 (100% identical), dog NEK7 (99% identical), pig NEK7 (99% identical), rat Nek7 (98% identical), mouse Nek7 (98% identical), macaque NEK7 (95% identical), tropical clawed frog nek7 (95% identical), guinea pig NEK7 (88% identical), zebrafish nek7 (86% identical), Caenorhabditis elegans nekl-3 (68% identical). Paralogues in human: NEK6 (79% identical), NEK8 (35% identical), NEK9 (35% identical), NEK10 (34% identical), NEK3 (34% identical), NEK2 (33% identical), NEK5 (32% identical), NEK11 (32% identical).
Diseases named in the same sentence as NEK7 in open-access papers:
NEK7 is named in the same sentence as 85 diseases in open-access papers, as found by Europe PMC text mining. Sharing a sentence is not in itself a finding about the gene and the disease. The quoted sentences say what the papers report.
hepatocellular carcinoma (8 papers, 2016 to 2024). A malignant tumor that arises from hepatocytes. "Furthermore, virus-mediated NEK7 silencing could inhibit the growth of hepatocellular carcinoma cell lines and tumor cells on the xenotransplantation model in immunodeficient mice." (PMID 34419048, 2021). "In this study, we investigated whether Nek7 involves in hepatocellular carcinoma (HCC)." (PMID 26921196, 2016). "CT01, a small-molecule glue targeting NEK7 developed by Captor Therapeutics, can induce the degradation of proteins including NEK7, GSPT1, and SALL4 and has been applied to the treatment of hepatocellular carcinoma, lung cancer, and NET tumors." (PMID 38791529, 2024). "In the present study, we investigated whether NEK7 is involved in cell pyroptosis of hepatocellular carcinoma (HCC)." (PMID 35223495, 2022). "Similarly, high NEK7 expression was also significantly correlated with hepatocellular carcinoma (HCC), with the degree of malignancy, as reflected in tumor numbers, tumor diameter, adjacent organ invasion, tumor grade, and TNM stage." (PMID 33364979, 2020). "NIMA-related kinase 7 (NEK7), which plays a crucial role in mitosis entry, cell cycle progression, cell division, and mitotic processes, has been proven to be a vital mediator during inflammasome activation in hepatocellular carcinoma." (PMID 34603335, 2021). "Additionally, hepatocellular carcinoma cell lines, such as HepG2, Hep3B, Huh7 and SMMC7721, presented high levels of NEK7 mRNA compared to LO2, a normal hepatic cell line." (PMID 32294979, 2020).
inflammatory bowel disease (8 papers, 2019 to 2025). A spectrum of small and large bowel inflammatory diseases of unknown etiology. "It has been shown that NEK7 (mitotic kinase) interacts with NLRP3 to regulate pyroptosis in inflammatory bowel disease (IBD) through the NF-κB signaling pathway." (PMID 37821972, 2023). "NEK7 was found to modulate the pyroptosis of MODE-K cells by interacting with NLRP3 in an inflammatory bowel disease (IBD) model." (PMID 36177039, 2022). "NEK7 has been reported to be interacted with NLRP3 to modulate the pyroptosis in inflammatory bowel disease via NF-κB signaling." (PMID 35991122, 2022). "The activated LRR region inhibits NLRP3 inflammasome activation through NEK7-NLRP3 complex with NIMA-related kinase 7 (NEK7), which plays an important role in AS, diabetes, Alzheimer's disease, and inflammatory bowel disease." (PMID 39742016, 2024). "For example, NEK7 regulates the activation of NLRP3 inflammasome and the subsequent pyroptosis through the interaction between NEK7 and NLRP3, thus influencing the advancement of inflammatory bowel disease." (PMID 37506161, 2023). "Notably, NF-κB signalling reportedly regulates the interaction of NEK7 and NLRP3, thereby modulating pyroptosis in inflammatory bowel disease." (PMID 39334337, 2024).
gout (7 papers, 2020 to 2025). A condition characterized by painful swelling of the joints, which is caused by deposition of urate crystals. "The aberrant expression of NEK7 has been implicated to the growth of metastasis and severe inflammatory conditions like rheumatoid arthritis, liver cirrhosis, and gout." (PMID 36922575, 2023). "A typical expression or any mutation in the genetic makeup of NEK7 leads to the development of cancer malignancies and fatal inflammatory disease, i.e., breast cancer, non-small cell lung cancer, gout, rheumatoid arthritis, and liver cirrhosis." (PMID 35807344, 2022). "Since NEK7 is critical for NLRP3 inflammasome activation, NEK7 inhibitors could be employed as therapeutic agents against gout, a representative disease caused by NLRP3 inflammasome." (PMID 38371945, 2023). "In our attempt to develop a novel inflammasome inhibitor blocking NEK7 action, we identified SLC3037, which could inhibit inflammasome activation by MSU, an effector of inflammasome activation associated with gout." (PMID 38371945, 2023). "We next studied whether improved clinical manifestation of gout and inflammation by the NEK7 inhibitor are due to inhibition of MSU-induced inflammasome in vivo." (PMID 38371945, 2023). "Besides promoting the proliferation of various resting cells, NEK7 is also involved in the progression and development of fatal inflammatory diseases, including Alzheimer’s disease, auto-immune disorders, inflammatory bowel disease, gout, and tumor formation." (PMID 35807344, 2022). "In an attempt to develop novel inhibitors of the NLRP3 inflammasome acting on NEK7, we identified an NLRP3 inhibitor blocking NEK7 binding to NLRP3 and investigated its effect on an MSU-induced gout animal model, which mimics human gout arthritis pathogenically linked to the inflammasome." (PMID 38371945, 2023). "The mRNA expression of NIMA-related kinase 7 (NEK7) and NLRP3 is upregulated in gout patients." (PMID 35464445, 2022). "SLC3037, an NLRP3 inhibitor that blocks NEK7 [never in mitosis A (NIMA)-related kinase 7 (NEK7) critical in NLRP3 oligomerization] binding to NLRP3, shows promise as a novel agent for diseases associated with NLRP3 inflammasome activation like gout." (PMID 39968300, 2025). "The findings indicate that curcumin may inhibit the assembly and activation of the NLRP3 inflammasome by directly targeting and disrupting the interaction between NEK7 and NLRP3, thus providing insight into curcumin's ability to mitigate gout‐related damage and inflammation." (PMID 41035515, 2025). "If NEK7 inhibitors without effects on kinase activity could be developed, such compounds could be valuable candidates against gout or other diseases characterized by the inflammasome such as cardiovascular diseases, metabolic syndrome, and neurodegenerative disorders." (PMID 38371945, 2023).
diabetes (6 papers, 2022 to 2025). "Increased expression of the NEK7 gene has been reported in patients with gestational diabetes, and suppression of NLRP3 inflammasome activation related to NEK7 overexpression has been shown to mitigate diabetes-induced muscle atrophy." (PMID 41465472, 2025). "In a rat model of diabetes, low levels of miR-23a in the liver targeted NIMA-related kinase 7 (NEK7), leading to its upregulation to activate pyroptosis caused by NLR Family Pyrin Domain Containing 3 (NLRP3) activation." (PMID 37371692, 2023). "Other studies in diabetes models found that, miR-23a-3p is also a member of the miR-23 family and can negatively regulate its downstream target gene NEK7 and inhibit NEK7-dependent NLRP3 activation." (PMID 36304156, 2022). "A previous study also showed that the expressions of NEK7 and NLRP3 inflammasome in vascular cells of patients with diabetes were significantly increased." (PMID 36248820, 2022). "Aerobic exercise is believed to be a promising intervention to reduce the expressions of ROS, NF-κB, NEK7, NLRP3, ASC, Caspase-1, IL-1β, and other inflammatory factors, and improves diabetes-induced inflammation and reduces insulin resistance." (PMID 36248820, 2022). "Therefore, 12 weeks of Tai Chi intervention can significantly decrease the expressions of NEK7, NLRP3, ASC, Caspase-1, GSDMD, IL-1β, and IL-18, while increasing the expression of irisin in pre-diabetes." (PMID 36248820, 2022).
breast carcinoma (5 papers, 2016 to 2022). "For example, NEK2 has an important role in centrosome separation and is implicated in breast cancer progression, while NEK6, NEK7 and NEK9 are involved in mitotic spindle assembly, which requires regulation of microtubule polymerization." (PMID 36550548, 2022). "A recent breast cancer-related study provides solid evidence that UNC45A nuclear localization promotes the expression of the mitotic kinase NEK7 and that the mitotic catastrophe resulting from UNC45A deficiency can be rescued by heterologous NEK7 expression." (PMID 33364979, 2020). "In addition, NEK7 also encourages the proliferation of resting cells, which indicates its high-level involvement in various cancer types, including non-small lung cancer, breast cancer, NLRP3-related inflammatory disease, and gastric cancer progression." (PMID 35807344, 2022). "Moreover, NEK7 is significantly increased in squamous cell carcinoma of the head and neck, breast cancer, colorectal cancer and lung cancer, and promotes the proliferation of liver cancer cells in vitro and in vivo, due to its significant relationship with Ki67 expression in HCC tissues." (PMID 34295827, 2021). "Similarly to NEK7, SOX4 has been identified as an important oncogene in a variety of other cancers including endometrial cancer, brain cancer, breast cancer, bladder cancer, ovarian cancer, colorectal cancer, liver cancer and leukemia." (PMID 27115612, 2016).
diabetic cardiomyopathy (5 papers, 2021 to 2025). Diabetic cardiomyopathy is a disorder of the heart muscle in people with diabetes. "Additionally, BMP7 alleviates pyroptosis and inflammation and improves cardiac dysfunction in diabetic cardiomyopathy by inhibiting the Nek7/GBP5 signaling axis, thus suppressing inflammasome formation in cardiomyocytes." (PMID 40636987, 2025). "Some studies observed that the NEK7/NLRP3 inflammasome-signaling pathway is involved in diabetic vascular injury or in inflammation-related diabetic cardiomyopathy, a type of sterile inflammation, with a role in oligomerization and activation of the NLRP3 inflammasome complex." (PMID 38338718, 2024). "Here, we report inflammation-induced cell death mediated by inflammatory cells (macrophage and dendritic cells) and inflammasome formation (TLR4, NLRP3) and NLRP3 activators (Nek7 and GBP5) that cause cardiac cell death is the key player in the development and progression of diabetic cardiomyopathy." (PMID 34685620, 2021). "In the context of diabetic cardiomyopathy, bone morphogenetic protein-7 (BMP-7) alleviated inflammation-induced pyroptosis by inhibiting the TLR4-NLRP3 complex, which is activated by GBP5 and NIMA-related kinase 7 (Nek7)." (PMID 40788157, 2025). "Interestingly, treatment with BMP-7 attenuated the increased expression of Nek7 (p = 0.038) and GBP5 (p = 0.01) compared to the diabetic group, suggesting that BMP-7 attenuates inflammasome protein regulators Nek7 and GBP5 prior to the initiation of NLRP3 upregulation in diabetic cardiomyopathy." (PMID 34685620, 2021). "The exact role of Nek7 and GBP5 in the heart as well as in diabetic cardiomyopathy has never been examined as per the best of our knowledge." (PMID 34685620, 2021).
lung carcinoma (5 papers, 2017 to 2025). "LUSC AAF Sub-cohort: The activation of NIMA kinases (NEK9, NEK6, NEK7) pathway is closely linked to lung cancer cell cycle control, as these kinases regulate mitotic spindle formation and chromosomal stability, and their overexpression promotes proliferation, invasion, and poor prognosis in NSCLC." (PMID 41228248, 2025). "The other kinase used to test this method was the serine/threonine protein kinase NEK7, which has roles in mitotic spindle formation, cytokinesis, and centrosome duplication, and which has been found over-expressed in breast, colorectal, laryngeal and lung cancer as well as in non-Hodgkin lymphoma." (PMID 28724347, 2017). "Initially, NEK7 was thought to be the downstream target of WHSC1L1 involved in human carcinogenesis through expression profile analysis in vitro using human bladder and lung cancer cell lines." (PMID 33364979, 2020). "Similarly, in a recent study, EML4-ALK variant 3(V3) was proposed to mediate microtubule stabilization through NEK7 and NEK9, accelerating cell migration in EML4-ALK lung cancer." (PMID 33364979, 2020).
Chronic colitis (4 papers, 2019 to 2024). A chronic inflammatory disease of the large intestine (colon, cecum and rectum). "Herein, we established a DSS-induced chronic colitis mouse model and conducted NEK7 knockdown by tail intravenous injection of Lsh NEK7." (PMID 31787755, 2019). "More relevantly, NEK7 interacted with NLRP3 to activate the NLRP3 inflammasome activation, thereby enhancing the pyroptosis in MODE-K cells and DSS-induced chronic colitis in mice." (PMID 38467948, 2024). "On one hand, NEK7 interacted with NLRP3 to regulate NLRP3 inflammasome activation, thereby modulating the pyroptosis in MODE-K cells and DSS-induced chronic colitis in mice." (PMID 38482005, 2024). "In conclusion, NEK7 interacts with NLRP3 to modulate NLRP3 inflammasome activation, therefore modulating the pyroptosis in MODE-K cells and DSS-induced chronic colitis in mice." (PMID 31787755, 2019). "NEK7 interacts with NLRP3 to modulate NLRP3 inflammasome activation, therefore modulating the pyroptosis in MODE-K cells and DSS-induced chronic colitis in mice." (PMID 31787755, 2019). "NEK7 knockdown abolish ATP + LPS-induced pyroptosis in vitro and improved DSS-induced chronic colitis in vivo." (PMID 31787755, 2019).
gallbladder cancer (4 papers, 2016 to 2022). "NEK7 can be highly expressed in gallbladder carcinoma, which is closely related to tumor differentiation, Nevin stage, and metastasis, and can significantly shorten the OS85." (PMID 35105934, 2022). "Additional studies found higher NEK7 expression levels in larynx, breast, colon/rectum and gallbladder cancer." (PMID 28724347, 2017). "Notably, in gallbladder cancer, a significant correlation was first observed between the increased protein expression of NEK7, FoxM1 and Plk1 and tumor differentiation, development and shorter overall survival time." (PMID 33364979, 2020). "Moreover, Nek7 is highly expressed in gallbladder cancer compared to normal tissues, and has significant relationship with tumor differentiation, metastasis and patients survival rate." (PMID 26921196, 2016). "However, how NEK7 is involved in gallbladder cancer needs to be further determined." (PMID 33364979, 2020). "Notably, it has been reported that Nek7 is overexpressed in gallbladder cancer tissues, however, until now there is no data about the expression pattern and biological role of Nek7 in HCC." (PMID 26921196, 2016).
liver cancer (4 papers, 2016 to 2025). An epithelial or non-epithelial malignant neoplasm that arises from the liver. "Ongoing targets like CHMP3, pir-hsa-216911, and NIMA-related kinase 7 (NEK7) continue to expand the therapeutic landscape of pyroptosis in liver cancer treatment." (PMID 41267084, 2025).
Sepsis (4 papers, 2022 to 2023). Sepsis is defined as life-threatening organ dysfunction caused by a dysregulated host response to infection. "Further mechanistic studies have revealed that WHSC1 exacerbates alveolar macrophage pyroptosis in sepsis-induced ALI through the NEK7-mediated activation of the NLRP3 inflammasome." (PMID 35967871, 2022). "In addition, miR-181a-5p is reported to target NIMA-related kinase 7 (NEK7), thereby inhibiting pyroptosis in sepsis-induced AKI mice." (PMID 37761260, 2023). "Unfortunately, the detailed mechanisms by which WHSC1 regulates NEK7 expression in sepsis have not been explored and require further study." (PMID 35967871, 2022).
systemic lupus erythematosus (4 papers, 2018 to 2023). An autoimmune multi-organ disease typically associated with vasculopathy and autoantibody production. "NEK7, a serine/threonine kinase implicated in mitosis, shows lower protein and mRNA levels in systemic lupus erythematosus (SLE) patients." (PMID 34603335, 2021). "Several other findings linking NEK7 with inflammation and inflammation-based diseases, such as diabetes, endometritis, systemic lupus erythematosus and various cancers, have been published." (PMID 32294979, 2020).